ATM (ATM serine/threonine kinase)
Diseases named in the same sentence as ATM in open-access papers (continued):
Sharing a sentence is not in itself a finding about the gene and the disease.
melanoma (119 papers, 2010 to 2026). A malignant, usually aggressive tumor composed of atypical, neoplastic melanocytes. "None of these variants have previously been linked to malignant melanoma, but several other germline variants in ATM have been found in patients with multiple malignant melanomas indicating a role for the gene in melanoma development." (PMID 40072281, 2025). "PARP4 deficiency sensitizes melanoma cell lines to treatment with ATM inhibitors (ATMi), thus attributing to it an active role as an oncoprotein in melanoma." (PMID 41463260, 2025). "In the index patient in family E01 (E01‐01), who had been treated for three primary melanomas, we found a complex insTGdelC variant in ATM resulting in a frameshift from H1082 and a premature termination of the protein after 13 amino acids." (PMID 40072281, 2025). "A variant of ATM, Ser49Cys (rs1800054; minor allele frequency = 0.011), has been associated with an elevated risk of melanoma development; however, the functional consequence of this variant is not defined." (PMID 38338943, 2024). "The limited data about the increased risk of melanoma associated with the ATM Ser49Cys variant are from a single study." (PMID 38338943, 2024). "In one of the AMGP melanomas from these germline carriers, ATM was hemizygous with the variant allele lost." (PMID 38338943, 2024). "Phospho-ATM loss is associated with early-stage tumor progression, tumor growth, and melanoma prognosis." (PMID 37674118, 2023). "To study the importance of ATM to PARPi treatment in melanoma on a functional level, we used the human melanoma cell line HT-144, that has the homozygous mutation p.W2845* in the ATM gene, resulting in a truncated and thereby inefficient ATM protein." (PMID 37674529, 2023). "We found that MAPK inhibitor resistant melanoma cells are particularly sensitive to PARP inhibitor treatment due to a lower basal expression of the DNA damage sensor ataxia-telangiectasia mutated (ATM)." (PMID 37674529, 2023). "Significantly, the SUMOylation-defective MITF-E318K melanoma predisposition mutation recapitulates the effects of ATM/DNA-PKcs-phosphorylated MITF." (PMID 37131595, 2023). "A large multicenter study demonstrated that ATM loss of function variants have a higher frequency in melanoma, compared to healthy individuals from a large multicenter melanoma cohort." (PMID 35563772, 2022). "In this study, ATM loss-of-function variants were observed in approximately 1% of melanoma patients, which was greater than that observed in samples from the Genome Aggregation Database (0.36%)." (PMID 35008949, 2022). "Recently, a large multicenter melanoma cohort investigating ATM germline PVs described ATM as a moderate-risk melanoma susceptibility gene." (PMID 35008949, 2022). "This is of particular relevance, as the identification of ATM as a melanoma-causative gene has potentially multiple clinical implications." (PMID 36555667, 2022). "Another analysis of individuals receiving germline MGP testing revealed that ATM PVs were associated with moderate risk of melanoma with an OR of 1.46 (95%CI, 1.18–1.81; p = 0.0006)." (PMID 35008949, 2022). "Two pathogenic variants (p.Ser1135_Lys1192del and p.Ser1993ArgfsTer23) showed LOH and complete loss of ATM activation in melanoma." (PMID 36555667, 2022). "Recently, germline PVs in the ATM gene have been found enriched in high-risk melanoma patients, and have been reported with a frequency of 1.06% in high-risk Italian melanoma patients." (PMID 36555667, 2022). "VUS analysis allowed us to explore not only the effect of ATM on melanoma, but also the effect of the variant itself on ATM function." (PMID 36555667, 2022). "As for the high proportion of melanoma-specific clonotypes observed in AT group, other studies also showed that mutations in ATM were associated with the risk of melanoma, and the change in phospho-ATM expression was associated with melanoma progression." (PMID 34825286, 2022).
melanoma (continued). "In the tumor samples of two patients with VUS, however, ATM expression was ≤50%, suggesting that these two germline variants represented the first of two hits that contributed to ATM deficiency and melanoma development." (PMID 36555667, 2022). "Although ATM single-nucleotide polymorphisms have been linked to melanoma, few functional alleles have been identified." (PMID 34262154, 2021). "Of these, 29 families with a single ATM variant showed evidence of cosegregation with melanoma in sequenced affected family members, and 9 probands showed partial cosegregation in their families." (PMID 34262154, 2021). "Conversely, higher rates of ATM mutations are observed in melanomas compared to breast and ovarian cancers." (PMID 34831002, 2021). "Mutations to the ATM gene have a 20% to 30% lifetime risk of lymphoid, gastric, breast, central nervous system and skin, including melanoma." (PMID 33763108, 2021). "In summary, the findings from this study support the designation of ATM as a moderate-risk melanoma susceptibility gene." (PMID 34262154, 2021). "This study, describing the largest multicenter melanoma cohort investigated for ATM germline variants, supports the role of ATM as a melanoma predisposition gene, with LOF variants suggesting a moderate-risk." (PMID 34262154, 2021). "Namely, The Cancer Genome Atlas Consortium (TCGA) found germline ATM LOF variants in only 3 of 470 (0.6%) melanoma patients analyzed for a pan-cancer ES study." (PMID 34262154, 2021). "As for ATM deep deletions (deep loss, possibly homozygous deletion as defined by cBiopostal), it is most frequently found in cervical cancer and melanoma, representing 2.4 and 2.3% of all cases, respectively." (PMID 33224881, 2020). "Altogether, 7/11 double mutation carriers (excluded from the analysis of clinicopathological data) carried at least one mutation in high-risk melanoma (POT1/CHEK2) or syndromic (ATM/WRN, BRCA1, BRCA2 (2x), CHEK2/RAD51D, NBN) genes." (PMID 33050356, 2020). "Strikingly, loss of p-ATM was seen to be more obviously associated with early stages of melanoma progression (stage I to stage II), and with tumor thickness, suggests a correlation between p-ATM expression and tumor growth." (PMID 26275218, 2015). "Nevertheless, our study demonstrates association between p-ATM expression, melanoma progression and patient survival, and encourages further research." (PMID 26275218, 2015). "In conclusion our findings show that loss of p-ATM expression and gain-in p-ATM expression are indicators of worse melanoma patient survival." (PMID 26275218, 2015). "Understandably, a high level of activated p-ATM is associated with transformation of melanoma into a more aggressive and malignant phenotype and thereby associated with poor prognosis." (PMID 26275218, 2015). "Accordingly, our findings illustrate an association between p-ATM expression, melanoma progression, and patient survival." (PMID 26275218, 2015). "We then asked if the loss of or gain in p-ATM expression was associated with 5-year survival of melanoma patients." (PMID 26275218, 2015). "Compound exhibited significant efficacy in suppressing the proliferation of ATM-deficient HT144 melanoma cells and displayed a favourable pharmacokinetic profile, positioning it as a promising agent for in vivo validation of the synthetic lethality paradigm between ATM loss and ATR inhibition." (PMID 40256842, 2025). "This study aimed to assess the impact of deleterious ATM variants on homologous recombination deficiency (HRD) and response to PARP inhibitors (PARPi) in melanoma patients, using a cell line established from melanoma tissue of a patient carrying the c.5979_5983del germline ATM variant." (PMID 40806549, 2025). "We previously proposed ATM (including this variant), as a candidate melanoma predisposition gene." (PMID 38750555, 2024).
melanoma (continued). "Chi-square analysis confirmed that the frequency of ATM Ser49Cys was significantly higher in a high-risk melanoma cohort (9/384 carriers; n = 7 multiple primary melanoma, n = 2 single primary melanoma) compared to the European cohort (non-Finnish) in GnomAD (p = 0.01)." (PMID 38338943, 2024). "This may suggest that comparable to GOLM1 Ser307Leu, the ATM Ser49Cys variant is associated with a lower risk of melanoma and/or a later age of onset." (PMID 38338943, 2024). "PTVs in ATM were associated with increased risks of nine cancers at p<0.001 (pancreas, oesophagus, lung, melanoma, breast, ovary, prostate, bladder, lymphoid leukaemia (LL)), and three at p<0.05 (colon, diffuse non-Hodgkin’s lymphoma (DNHL), rectosigmoid junction)." (PMID 39209703, 2024). "A large multicentre study of familial, multiple primary (MPM) and sporadic melanoma cases found a significant association with ATM germline variants of unknown significance (VUS) suggesting these conferred a moderately increased risk of developing melanoma." (PMID 38338943, 2024). "Following the identification of ATM germline variants in melanoma patients and the emergence of ATM as a melanoma Genome-Wide Association Study hit, a multicentric international study on 2105 melanoma cases proposed ATM as an intermediate-risk melanoma predisposition gene." (PMID 36901733, 2023). "To confirm the involvement of ATM kinase in the molecular mechanisms underlying the effects of chrysin, we treated melanoma cell lines for 72 h with polyphenol (40 and 80 μM) in the absence or presence of a specific pharmacological inhibitor of ATM (KU55933, 10 μM, ATMi)." (PMID 37371032, 2023). "On the other hand, monoallelic ATM germline variants have been shown to be associated with an increased risk of developing malignancies, including breast, pancreatic, prostate, stomach, ovarian, colorectal, and melanoma." (PMID 38201484, 2023). "In addition, a recent study reported loss of ATM expression in melanoma samples from germline ATM PV carriers, supporting the role of this gene in melanoma predisposition." (PMID 36901733, 2023). "However, the association of ATM with melanoma needs functional assessment starting from LOH analysis to definitively include this tumor in the ATM-related cancer spectrum." (PMID 36555667, 2022). "ATM germline pathogenic variants were recently found enriched in high-risk melanoma patients." (PMID 36555667, 2022). "In this regard, increased expression levels of phosphorylated ATM at ser-1981, which is an activated form of ATM induced by ROS, were observed in melanoma samples, and also were associated with tumor progression toward a more aggressive and malignant phenotype with poor prognosis in patients." (PMID 35804995, 2022). "In a recent multicentric international study on 2105 melanoma cases, we associated germline heterozygous variants in ATM with melanoma risk, therefore proposing ATM, which was previously established as a melanoma genome-wide association study (GWAS) hit, as a melanoma intermediate-risk gene." (PMID 36555667, 2022). "The molecular mechanism of SL-mediated G2/M arrest and apoptosis in melanoma cell lines suggests that SLs are possible alkylating agents that might cause DNA damage, which activates the kinase ATM/ATR." (PMID 36359261, 2022). "In addition, we recently found ATM LOF or potentially deleterious variants in up to 3% of high-risk melanoma patients." (PMID 34262154, 2021). "Moreover, an assessment of the magnitude of ATM risk in melanoma will be crucial to determine the potential clinical utility of germline ATM testing in terms of surveillance." (PMID 34262154, 2021). "We thus hypothesize that the loss of function of one copy of the ATM gene could have contributed to her melanoma." (PMID 33763108, 2021).
melanoma (continued). "Furthermore, the same team demonstrates that ferroptosis can be triggered by the combined action of IFN-γ and ataxia-telangiectasia mutated (ATM) activated by radiotherapy in melanoma cells and human fibrosarcoma cells." (PMID 33540645, 2021). "The findings of genome-wide association studies (GWASs) suggest that ATM may be a low-risk melanoma susceptibility locus, but functional alleles have not yet been identified." (PMID 32325837, 2020). "Regarding melanoma, while risk estimates were not reliable for most genes due to a smaller melanoma cohort size, PVs in CDKN2A were expectedly associated with very high risks for melanoma (OR = 114.6); however, PVs in ATM and BRCA1 were also elevated (two- to threefold increased risks)." (PMID 31406321, 2020). "ATM somatic mutations are also frequent in melanoma (~9.2%) and lung adenocarcinoma (~8.1%)." (PMID 33224881, 2020). "In addition, telomere-related loci have been associated with risk of melanoma in GWAS including: ATM, TERT, and more recently, OBFC1." (PMID 28212542, 2017). "From the iPSC mutation patterns in this study, the mutation signature of XPA-iPSCs is suggested to resemble to Signature 1B, 7 or 14, which are strongly related to melanoma, while those of ATM-deficient iPSCs resemble to Signature 5 and 9, lymphoma-related signatures." (PMID 27197874, 2016). "Moreover, inhibiting PARP4 could improve melanoma cell sensitivity to Ataxia telangiectasia mutated (ATM) inhibitors in vitro and in vivo." (PMID 39885134, 2025). "Indeed, the inclusion of ATM in melanoma multi-gene diagnostic panels would increase the number of high-risk individuals identified through genetic testing who could benefit from dermatologic surveillance." (PMID 36555667, 2022). "Therefore, the ATM impact on melanoma predisposition is unclear." (PMID 36555667, 2022). "Moreover, CNV analysis of WES data revealed a whole-gene deletion on the WT ATM allele in both samples, which was confirmed by Sanger sequencing and microsatellite analysis, showing loss of the WT allele in both tissues and in the melanoma cell line." (PMID 36555667, 2022). "Indeed, the association with melanoma was maintained for VUS outside ATM functional domains, which may be consistent with this latter hypothesis." (PMID 34262154, 2021). "Therefore, the association of ATM pathogenic variants with melanoma could be higher than the one we observed." (PMID 34262154, 2021). "Therefore, ATM impact on melanoma predisposition is unclear." (PMID 34262154, 2021). "Taken together, tRA combined with an ATM inhibitor can greatly enhance the anti-angiogenic activity of SerRS under UV irradiation and could be a better strategy in protecting skin from angiogenesis-associated skin damage and melanoma caused by UV radiation." (PMID 31766690, 2019). "Molecular profiling confirmed the diagnosis of melanoma and identified mutations in the TERT promoter, NRAS, NF1, PBRM1, FAT1, and ATM genes." (PMID 40125165, 2025). "Our study highlighted the crucial role of PARP4 in DNA damage repair and its impact on the sensitivity of ATM inhibitor in melanoma therapy." (PMID 39885134, 2025). "In conclusion, we provided evidence that SRA737 + LDHU activates NF-κB in human melanoma cells through the canonical pathway activated by the DNA damage response via ATM." (PMID 40507298, 2025). "We have previously identified a family with a history of early-onset melanoma and astrocytoma with an allelic loss of function of CDKN2A p14ARF-specific transcript mutation (c.193G>A; p.G65S) and the ATM Ser49Cys allele." (PMID 38338943, 2024). "Of interest, the MAF of ATM Ser49Cys (MAF = 0.007), is comparable to that of the known moderate-penetrance melanoma MITF germline variant Glu318Lys (MAF = 0.001) and also the suspected GOLM1 modifier variant Ser307Leu (MAF = 0.003)." (PMID 38338943, 2024).
melanoma (continued). "Still, further experimental work in preclinical models will be required to determine the therapeutic relevance of MRN complex alterations and ATM downregulation in melanoma, as well as the functional consequences of SVs at recurrently altered TAD boundaries." (PMID 38758740, 2024). "Three genes of the final associative network, CASP8, ATM, and PARP1, are associated in GWAS with melanoma as an example of positive associations of cancer with neurodegenerative disorders characterizing different molecular pathophysiology." (PMID 37298337, 2023). "We show that MAPK inhibitor resistant melanoma cells exhibit low ATM expression increasing their sensitivity toward PARP inhibitors and that a combination of MAPK/PARP inhibitors act synthetically lethal in melanoma cells." (PMID 37674529, 2023). "ATM mRNA levels were significantly reduced in MAPKi resistant melanoma samples compared with samples of the same patient before the onset of MAPKi resistance." (PMID 37674529, 2023). "ATM inhibition led to efficient radiosensitization during colony forming in melanoma cells, while healthy tissue fibroblasts were merely affected in a RT-related manner." (PMID 36229655, 2023). "We validated the clinical relevance of our findings by ATM expression analysis in biopsies from patients with melanoma before and after development of resistance to MAPK inhibitors." (PMID 37674529, 2023). "Aside from the complex tumor spheroids grown from the patient-derived melanoma line 425362-245-T-J1, the ATM inhibitor AZD-1390 only showed activities near 10 μmol/L." (PMID 37637936, 2023). "Taken together, our results provide, for the first time, experimental data in support of the role of ATM impairment in melanoma development, showing a classic two-hit scenario in a well-known tumor suppressor gene." (PMID 36555667, 2022). "No histopathological and molecular features have been studied in melanomas developed by carriers of germline ATM PV or VUS." (PMID 36555667, 2022). "With this study, we wanted to determine the role of ATM disruption in melanoma development by integrating multiple in vitro assays." (PMID 36555667, 2022). "This study, showing a classic two-hit scenario in a well-known tumor suppressor gene, supports the inclusion of melanoma in the ATM-related cancer spectrum." (PMID 36555667, 2022). "Somatic ATM mutations rarely occur in melanoma (2.6%), and the literature on ATM protein expression and its clinical significance in melanoma is scant, although Bhandaru et Al." (PMID 36555667, 2022). "Along with the elevated RAD50 expression, enhanced ATM and increased p‐ATM levels were observed in metastatic melanoma cells with ILF2‐OV." (PMID 34709752, 2021). "Blocking PARP-1, ATM, or NF-κB in melanoma cells prevents the secretion of chemokine CCL2 thereby restricting the deleterious pro-invasive properties of the inflammatory SASP mediated by PNAS." (PMID 33855023, 2021). "Subsequently, the same team reported that IFN-γ derived from immunotherapy-activated CD8 + T cells synergizes with radiotherapy-activated ataxia-telangiectasia mutated (ATM) to induce ferroptosis in human fibrosarcoma cells and melanoma cells." (PMID 34475496, 2021). "Thus, it is possible a defective activation of this pathway leads to malignant transformation and, if this is the case, ATM penetrance could be modulated by UV exposure and/or the co-occurrence of other inherited melanoma predisposing factors, such as phototype and MC1R variants." (PMID 34262154, 2021). "The association between ATM VUS, especially those located in functional domains, and melanoma was weaker than that observed for LOF variants." (PMID 34262154, 2021). "Using RNA‐Seq data from the TCGA SKCM database, RAD50, NBS1, MRE11 and ATM expression were analysed in melanoma tissues." (PMID 34709752, 2021).